TGFBR1 (transforming growth factor beta receptor 1)
Diseases named in the same sentence as TGFBR1 in open-access papers (continued):
Sharing a sentence is not in itself a finding about the gene and the disease.
preeclampsia (3 papers, 2017 to 2021). Preeclampsia is a hypertensive disorder of pregnancy that is characterized by new-onset hypertension with proteinuria presenting after 20 weeks of gestation, and depending on mild or severe forms may initially present with severe headache, visual disturbances, and hyperreflexia. "We have previously demonstrated that variation in TGFβR1[ALK5] was associated with preeclampsia in an African American cohort." (PMID 29580923, 2018). "However, we identified other associations between ENG pathway candidate genes and preeclampsia in the Norwegian (TGFβR1[ALK5], TGFβR2) and Latina (ALK1, TGFβR2) cohorts in our adjusted models." (PMID 29580923, 2018). "Genetic variation in TGFβR1[ALK5] and TGFβR2 was associated with susceptibility to/protection from preeclampsia in the Norwegian cohort, while genetic variation in ALK1 and TGFβR2 was associated with susceptibility to/protection from preeclampsia in the Latina cohort." (PMID 29580923, 2018). "Independent of preeclampsia, apical insoluble DRMs and placental-derived (PLAP-immunoprecipitated) exosomes contained the type 1 receptor TGFBR1 (ALK5)." (PMID 28939895, 2017).
acute myeloid leukemia (2 papers, 2010 to 2020). Acute myeloid leukemia (AML) is a group of neoplasms arising from precursor cells committed to the myeloid cell-line differentiation. "Of interest, afadin (AFDN) and TGF-beta receptor type-1 (TGFBR1) are also involved in acute myeloid leukemia (also enriched in oxidized transcripts)." (PMID 32699268, 2020).
anal carcinoma (2 papers, 2013 to 2017). "Biomarker analyses demonstrated that the activation of the Akt pathway in ASCC of the Tgfbr1 and Pten double knockout (2cKO) mouse was similar to that observed in human anal cancer." (PMID 24124460, 2013). "We previously developed Tgfbr1 conditional knockout mice with Neurofilament-H- Cre, which develop anal cancer over a long period of about 4–6 months." (PMID 24124460, 2013). "Here we report that Tgfbr1/Pten double conditional knockout mice spontaneously develop anal cancer in a short period of time with activation of the Akt/mTOR pathway and without carcinogen induction." (PMID 24124460, 2013). "Pten cKO mice and Tgfbr1 cKO mice (even with one dose of 50 mg DMBA) did not develop anal cancer during observation of more than one year." (PMID 24124460, 2013).
arachnodactyly (2 papers, 2024 to 2025). "Genetic variants in genes including TGFBR1, TGFBR2, TGFB2, TGFB3, SMAD2, and SMAD3 result in Loeys–Dietz syndrome and are reported to cause Marfan-like phenotypes and variants in FBN2 and COL3A1 result in congenital contractural arachnodactyly and Ehlers–Danlos syndrome type IV." (PMID 38791509, 2024).
Arthritis (2 papers, 2007 to 2015). Inflammation of a joint. "Whereas this study provides the first report concerning the expression of TGFBR1 in human arthritis, the type II receptor and endoglin (a receptor for TGF-β1 and 3) have been reported to be more strongly expressed in RA SM than in OA SM or normal SM, showing the relevance of TGF-β-signaling in RA." (PMID 17594488, 2007).
Bicuspid aortic valve (2 papers, 2013 to 2024). The presence of an aortic valve with two instead of the normal three cusps (flaps). "The purpose of our study was to investigate the potential contribution of germline mutations in NOTCH1, GATA5 and TGFBR1 and TGFBR2 genes in a cohort of Italian patients with familial Bicuspid Aortic Valve (BAV)." (PMID 23578328, 2013).
bladder tumor (2 papers, 2016 to 2019). "In conclusion, this study demonstrated that genetic deletion of Tgfbr2 or treatment of Tgfbr1 small molecule inhibitor LY364947 led to decrease of bladder tumor invasion and progression." (PMID 27378170, 2016).
colitis (2 papers, 2021 to 2023). Inflammation of the colon. "Similarly, Tgfbr1f/fTCRδ ER Cre mice were also more vulnerable and exhibited worse inflammation in response to DSS-induced colitis than Tgfbr1+/+TCRδ ER Cre control mice." (PMID 37253786, 2023). "Our data also suggest changes in cytokine receptor gene expression on MulTreg, which may include a shift from IL-10 and IL-27 induced regulatory function towards enhanced TGFBR1 signaling which has been shown to induce Treg retention in inflamed sites and control of experimental colitis." (PMID 34539651, 2021).
craniosynostosis (2 papers, 2016 to 2020). Craniosynostosis is defined as the premature fusion of one or more cranial sutures leading to secondary distortion of skull shape resulting in skull deformities with a variable presentation. "This frequency is much greater than any other genotype causing syndromic midline craniosynostosis (e.g., TGFBR1/2, SKI, RUNX2), which are sufficiently rare that their prevalence has not been well-established." (PMID 27606499, 2016).
Crohn disease (2 papers, 2024). A gastrointestinal disorder characterized by chronic inflammation involving all layers of the intestinal wall, noncaseating granulomas affecting the intestinal wall and regional lymph nodes, and transmural fibrosis. "This GI-restricted inhibitor of TGFβR1 (ALK5) is specifically engineered to target TGFβ signalling, an essential regulator of fibrosis, with the goal of decreasing the necessity for bowel resection surgery in individuals with fibro-stenotic Crohn’s disease." (PMID 39684719, 2024). "IFNγ+ ILC1s were accumulated in the intestine of Crohn’s disease patients with low expression levels of TET1 and TGFBR1." (PMID 38839760, 2024).
endometrial tumors (2 papers, 2020 to 2024). "In agreement with our observations, an independent study of a Tgfbr1 and Pten double conditional knockout mouse exhibited rapidly progressing endometrial tumors that exhibited myometrial invasion, which remarkably resembled the phenotypes observed in iPAD mice." (PMID 32483112, 2020).
female infertility (2 papers, 2011 to 2018). Diminished or absent ability of a female to achieve conception. "Our earlier studies have reported that overactivation of TGFB receptor 1 (TGFBR1) in the mouse uterus using progesterone receptor (Pgr)-Cre recombinase causes female infertility, defective decidualization, and reduced uterine gland formation, a developmental milestone of postnatal uterus." (PMID 30550590, 2018). "To define the causes of female sterility, we examined the ovaries of the Tgfbr1 cKO mice." (PMID 22028666, 2011). "In the current study, conditional deletion of Tgfbr1 in the female reproductive tract using Amhr2-Cre expressed in granulosa cells and mesenchymal compartments of the oviduct and uterus led to female sterility." (PMID 22028666, 2011).
fibrosarcoma (2 papers, 2019 to 2024). A malignant mesenchymal fibroblastic neoplasm affecting the soft tissue and bone. "The expression of TGFBR1 in NK cells can enhance cancer cell metastasis and accelerate the growth of fibrosarcoma, indicating that TGF-β activates SMAD4 to inhibit NK cell-mediated monitoring in cancer metastasis." (PMID 38514720, 2024).
gastric adenocarcinoma (2 papers, 2009 to 2024). "M2 macrophages also showed a preferential expression of TGFBR1 and TGFBR2 genes in colon, lung, and stomach adenocarcinomas based on TCGA database." (PMID 38441961, 2024).
hepatitis C (2 papers, 2023 to 2024). "The risk of developing hepatitis C aftertransplantation in patients was shown to be associated with the frequency ofthe SNP rs868 located in the non-coding 3′-UTR region of the TGF-β1receptor gene (Tgfbr1)." (PMID 37908775, 2023). "The rs868 SNP, located in the 3′-UTR of the TGFBR1 gene, has been shown to have a regulatory effect on miRNA/mRNA interaction by influencing negative RNA correlation in patients with hepatitis C-associated end-stage liver disease." (PMID 39684686, 2024).
Hernia (2 papers, 2020 to 2025). "Pgr+ fibroblasts likely play a central role in this process of hernia development, as they are upregulated in EP LAM and have increased expression of Tgfb2, Tgfbr1, and Tgfbr2." (PMID 40504614, 2025). "Together, our results show that PIK3R1, PTPN11, TGFBR1, CDC42, and SOS1 are probably the most essential proteins involved in human hernia formation." (PMID 31910207, 2020).
intestinal tumours (2 papers, 2011 to 2022). "A subsequent report showed that APCMin/+;Tgfbr1+/− mice developed twice as many intestinal tumours and colonic carcinomas as APCMin/+;Tgfbr1+/+, supporting the role of TGFBR1 gene haploinsufficiency in CRC development." (PMID 21224855, 2011).
ischemic stroke (2 papers, 2021 to 2023). A stroke disorder caused by obstruction of blood flow to the brain, due to thrombotic (local blood clot formation) or embolic (due to a blood clot or other material traveling from another site) event. "let-7e-5p expression is correlated with MAP kinase activation that involves CASP3 and TGFBR1, serving as a biomarker for ischemic stroke." (PMID 37624035, 2023).
keratoacanthoma (2 papers, 2020 to 2024). A dome-shaped, rapidly growing skin lesion composed of well differentiated squamous cells. "A 56 year old man with a five year history of keratoacanthomas over his arms, face and scalp was found to be carrying a TGFBR1 missense variant (c.664G > A, p.(Gly222Arg)), resulting in substitution of a glycine residue by an arginine at position 222 within the serine/threonine kinase domain." (PMID 33256177, 2020). "Testing for pathogenic TGFBR1 variants can help distinguish between MSSE and conditions such Lynch syndrome in which multiple keratoacanthomas can occur." (PMID 33256177, 2020).
kidney failure (2 papers, 2020 to 2025). An acute or chronic condition that is characterized by the inability of the kidneys to adequately filter the blood. "FXR activation increases the miR-135a-5p expression, thereby inhibiting the activation of the TGFBR1/TAK1 pathway, and resulting in the attenuation of vascular inflammation and calcification in CKD rats without repairing kidney failure." (PMID 32581266, 2020).
kidney inflammation (2 papers, 2021 to 2025). "Although there is no available genetic data for the role of TGFBR1 in kidney disease including DN, inhibition of TGFBR1 by the specific pharmaceutical inhibitors IN-1130 and SB-525334 can inhibit fibrosis in the rat models of UUO and puromycin aminonucleoside (PAN)-induced nephritis, respectively." (PMID 34360646, 2021).
Loeys-Dietz 1 syndrome (2 papers, 2021 to 2023). "Loeys-Dietz syndrome type 1 (LDS1) is caused by a mutation in the transforming growth factor-beta receptor 1 (TGFBR1) gene." (PMID 41552405, 2021).
lymph node metastasis (2 papers, 2015 to 2021). "Five genes (VEGFA, IFNB1, IGF1, TEK, and TGFBR1) are associated with angiogenesis, which provides clues to the mechanism of the association between epigenetic inactivation of CYB5R2 and lymph node metastasis." (PMID 26275421, 2015).
Marfan syndrome type 2 (2 papers, 2013 to 2025). "Loeys–Dietz syndrome, also known as Marfan syndrome type II, is a rare connective tissue disorder caused by dominant mutations in transforming growth factor-beta receptors (TGFBR1 and 2)." (PMID 24220024, 2013).
Micrognathia (2 papers, 2024). Developmental hypoplasia of the mandible. "Transforming growth factor beta (TGF-β) signaling is critical to craniofacial development by directing bone resorption and formation, and heterozygous mutations in the TGF-β type I receptor (TGFBR1) are associated with micrognathia in humans." (PMID 39473613, 2024). "Transforming growth factor beta (TGF-β) signaling is critical to craniofacial development by directing bone resorption and formation, and heterozygous mutations in TGF-β type I receptor (TGFBR1) are associated with micrognathia in humans." (PMID 38826301, 2024).
multiple sclerosis (2 papers, 2017 to 2020). A progressive autoimmune disorder affecting the central nervous system resulting in demyelination. "These miRNAs negatively regulated the TGFβ pathway (TGFBR1 and SMAD4 were significantly reduced in patients with multiple sclerosis), resulting in a decreased capacity of naive CD4 T cells to generate regulatory T cells." (PMID 32973667, 2020).
myelofibrosis (2 papers, 2020 to 2022). A partial or complete replacement of the bone marrow stroma by fibrous tissue. "This can lead to the hypothesis that myelofibrosis‐derived fibroblasts, acting as cancer‐associated fibroblasts, are highly dependent on TGFBR1, with a possible compensatory down‐regulation of TGFBR2." (PMID 32889753, 2020). "Likewise, treatment with an inhibitor targeting TGFBR1 (ALK5) reduced myelofibrosis in mouse models of MPNs." (PMID 35439167, 2022).
myeloma (2 papers, 2017 to 2021). "The underlying mechanism of ActivinA/SMAD1/5 signaling is not fully understood but suggests ACVR1 dependency and independency of ACVR1B/C/TGFBR1 as demonstrated by inhibitor experiments in FOP iECs being in line with knockdown studies in FOP and myeloma cells." (PMID 33410098, 2021).
Nephropathy (2 papers, 2007 to 2021). A nonspecific term referring to disease or damage of the kidneys. "In resequencing the genes we identified eight novel variants for TGFB1, TGFBR1 and TGFBR2 genes but did not detect significant association between any of the common SNPs and nephropathy in this Caucasian population with type 1 diabetes." (PMID 17319955, 2007).
osteomyelitis (2 papers, 2021 to 2025). An acute or chronic inflammation of the bone and its structures due to infection with pyogenic bacteria. "We next investigated the clinical significance of PCD pathways by correlating their GSVA scores with representative inflammatory biomarkers of osteomyelitis, including IL6R, MMP8, TNFRSF11A, IL17RB, TNFSF14, and TGFBR1." (PMID 41050653, 2025).
Parkinson disease (2 papers, 2020 to 2024). A progressive degenerative disorder of the central nervous system characterized by loss of dopamine producing neurons in the substantia nigra and the presence of Lewy bodies in the substantia nigra and locus coeruleus. "In contrast, expression of homeostatic markers such as CX3CR1 and TGFBR1, as well as MERTK were unaffected by in vitro α-syn PFF exposure, suggesting α-syn fibrils are direct drivers of some, but not all, microglial transcriptomic changes in late-stage Parkinson’s disease/Lewy body dementia." (PMID 37671615, 2024).
Patent ductus arteriosus (2 papers, 2018 to 2023). In utero, the ductus arteriosus (DA) serves to divert ventricular output away from the lungs and toward the placenta by connecting the main pulmonary artery to the descending aorta. "Meanwhile, transforming growth factor beta (TGF-β) receptor type 1 (TGFBR1) and TGFBR2 gene alterations are linked to patent ductus arteriosus." (PMID 36344649, 2023).
periodontitis (2 papers, 2019 to 2025). An acute or chronic inflammatory process that affects the tissues that surround and support the teeth. "EV-derived miR-128-3p from LPS-induced periodontitis may cause renal inflammation and be mediated by the Rps6kb1, Tgfbr1, and Acvr1 genes through the TGF-β signaling pathway." (PMID 41440335, 2025).
Testicular Tumors (2 papers, 2016 to 2023). "Thus, proliferation of Sertoli cells upon overactivation of TGFBR1 contributes to testicular tumor development." (PMID 38067144, 2023). "It is noteworthy that the tumor phenotype was not restricted to females, and males with constitutively active TGFBR1 (i.e., TGFBR1CA Lox/+; Amhr2-Cre) also developed testicular tumors (unpublished data that will be described in an independent report)." (PMID 27344183, 2016).
thyroid (2 papers, 2019 to 2021). "Furthermore, we analyzed the mRNA expression pattern of TGFB1, TGFBR1, and TGFBR2 in malignant and benign thyroid tissues." (PMID 33905626, 2021). "TGFBR1 is a receptor of TGF-β ligands and could be correlated with thyroid tumorigenesis." (PMID 31824949, 2019).
triple-negative breast carcinoma (2 papers, 2021 to 2023). An invasive breast carcinoma which is negative for expression of estrogen receptor (ER), progesterone receptor (PR), and human epidermal growth factor receptor 2 (HER2). "The lncRNA WT1-AS suppresses migration and invasion by targeting transforming growth factor beta receptor 1 (TGFBR1) in triple-negative breast cancer cells." (PMID 33152223, 2021).
adhesive capsulitis (1 paper, 2022). "Then, to inhibit Tgfbr1 expression, we constructed a siRNA-loading liposome and proved that this artificial agent, mimicking the protective function of these circulating exosomes, had therapeutic potential against adhesive capsulitis." (PMID 35986376, 2022).
anal squamous cell carcinoma (1 paper, 2013). A squamous cell carcinoma (SCC) arising from the anal canal or the anal margin (perianal skin). "Here we describe a mouse model with spontaneous anal squamous cell cancer, wherein a combined deletion of Tgfbr1 and Pten in stratified squamous epithelia was induced using inducible K14-Cre." (PMID 24124460, 2013).
anal tumors (1 paper, 2013). "Increased staining for Ki67, a hallmark of proliferation, was also observed in 2cKO mouse anal tumors as compared with Tgfbr1/Pten 2cKO perianal skin (P<0.01) and Tgfbr1flox/flox/Ptenflox/flox perianal skin (P<0.01)." (PMID 24124460, 2013).
atopic dermatitis (1 paper, 2025). "TGFBR1/2 variants can also lead to persistent, itchy, and inflamed skin, consistent with atopic dermatitis." (PMID 39859044, 2025). "These variants in TGFBR1/2 disrupt skin barrier homeostasis, increasing susceptibility to allergens and irritants, thereby worsening atopic dermatitis." (PMID 39859044, 2025).
calcification (1 paper, 2020). Process by which organic tissue becomes hardened by the physiologic deposit of calcium salts. "Our findings suggest that the activation of the TGFBR1/TAK1 pathway is involved in the pathological process of vascular calcification, and that miR-135a-5p is a key regulator of the TGFBR1/TAK1 pathway." (PMID 32581266, 2020). "Therefore to our knowledge, our study is the first to discover that the TGFBR1/TAK1 pathway-mediated HASMC inflammation is involved in the pathological process of vascular calcification; the inhibition of this inflammation could serve as a new therapeutic target for retarding vascular calcification." (PMID 32581266, 2020).
Charcot-Marie-Tooth disease type 1A (1 paper, 2019). Charcot-Marie-Tooth disease type 1A (CMT1A) is a type ofinherited neurological disorder that affects the peripheral nerves. "Muscle biopsy and genetic testing regarding Charcot-Marie-Tooth disease type 1A (CMT1A), Friedrichs ataxia (trinucleotide repeat in FXN), Loeys-Dietz syndrome (TGFBR1, TGFBR2) and Ehler Danlos syndrome type IV (COL3A1) were all normal as well as the karyotype of lymphocytes (46,XX)." (PMID 31053103, 2019).
chronic myeloid leukemia (1 paper, 2023). "KEGG analysis in the BaF3-T315 cells showed that the chronic myeloid leukemia signaling pathway (genes such as Cdk4, Tgfbr1, Gadd45b, Mdm2, Gadd45g, Polk, Rb1, Ctbp1, and Cdkn2a were enriched) was involved in the I13 treatment." (PMID 37124196, 2023).
cognitive disease (1 paper, 2022). "Interestingly, when we considered proteins which were significantly different in their SD between the healthy old and the old with cognitive disease and between the healthy young and healthy old, there were just 4 such proteins: Smad5, uPAR, FADD, and TGFBR1." (PMID 35999337, 2022).
colorectal adenocarcinoma (1 paper, 2020). The most common type of colorectal carcinoma. "Meanwhile, another study found the relation between expression of CEA (CEACAM5) gene and TGF-β pathway genes (TGFBR1, TGFBR2, and SMAD3) in colorectal adenocarcinoma cells." (PMID 33123542, 2020).